CD4 (CD4 molecule)
Diseases named in the same sentence as CD4 in open-access papers (continued):
Sharing a sentence is not in itself a finding about the gene and the disease.
Granuloma (continued). "Compared to BCG-induced granulomas, where the ratio of CD4+:CD8+ T cells was 3:1, their number was significantly (p ≤ 0.05) increased in VPM1002-, PDX- and NUOG-induced granulomas, resulting in CD4+:CD8+ T cell ratios of 1.4:1, 1:1 and 0.6:1, respectively." (PMID 36232295, 2022). "The release of IL-5 by CD4+ T lymphocytes, a key cytokine involved in the development and activation of eosinophils, leads to eosinophil recruitment to tissue sites in which granulomas are in the process of formation around parasite eggs." (PMID 36296298, 2022). "These colon‐recruited CD4+ CD25+ Tregs were found to be strong modulators of Th2 responses including granuloma size and eosinophilia, suggesting a role in intestinal schistosomiasis modulation." (PMID 32692855, 2021). "CXCR3+ CD4 T cells are efficient in localizing lung parenchyma around the lymphocytic cuff of TB granulomas and rarely in the myeloid core." (PMID 34745081, 2021). "During chronic stages of infection, there was an approximate fourfold increase in CD4+ CD25+ Foxp3+ Tregs in colonic granulomas, evidenced by an increase in the intestinal homing markers CD103+ and CCR5+." (PMID 32692855, 2021). "In contrast to wild-type granulomas, CD4+ T cells in mice expressing a monoclonal population of BCG-specific T cells have a resting phenotype." (PMID 34943793, 2021). "CD4-positive T cells were accumulated in the peribronchial region and the center of granulomas in all genotypes 60 days after MAC infection." (PMID 34504192, 2021). "Our results showed that a great number of CD4 T cells were recruited into the surrounding area of granulomas in the livers of WT mice at 7 dpi and 14 dpi." (PMID 34912336, 2021). "The pathogenesis of pulmonary sarcoidosis involves antigen presentation followed by CD4+ activation in regional lymph nodes, and subsequent organization of macrophages into granulomas." (PMID 33615672, 2021). "In GCA granulomas, instead, CD4 T cells and highly activated macrophages are characteristically present." (PMID 33917502, 2021). "The granulomas were comprised of CD4+ and CD68+ cells, indicating that they formed by the accumulation of CD4+ T-lymphocytes and macrophages." (PMID 33602264, 2021). "Consistently, it has been shown that BCG-induced granuloma T cells express a diverse TCR repertoire, but single specificity of CD4+ T cells is required to form the granuloma and control the BCG infection." (PMID 32093256, 2020). "CD4 depleted animals had significantly fewer CD4 T cells within granulomas compared to Mtb/SIV co-infected and Mtb-only control animals." (PMID 32730321, 2020). "CD4 depleted animals had fewer new granulomas during early reactivation and many were sterile suggesting that CD4 independent mechanisms for Mtb killing exist within the granuloma during LTBI as others have suggested." (PMID 32730321, 2020). "The presence of giant cells, granulomas, vascular deposition of IgM and C3, CD4 T-cell involvement, and an increased expression of HLA-B15 in both GA and GCA lends credence to the possibility of a shared pathophysiologic mechanism." (PMID 32872212, 2020). "After infection with S. mansoni, the percentage of granuloma nTregs (CD4+ CD25+ Foxp3+) has a significant increase at 8 and 16 weeks of the infection." (PMID 32132991, 2020). "M. marinum granulomas in zebrafish are well organized and histologically highly similar to Mtb granulomas, with their necrotic centres surrounded by infected macrophages, epithelial cells and infiltrating CD4+ cells and neutrophils." (PMID 32859577, 2020). "For example, only a minority of CD4+ T cells isolated from granulomas produce cytokines in responses to Mtb antigens, and only a handful appear positioned in proximity to Mtb-infected myeloid cells." (PMID 32793199, 2020). "Earlier studies in experimental schistosomiasis have shown the essential role for CD4+ T cells in granuloma formation and disease." (PMID 31950032, 2019).
Granuloma (continued). "In untreated conditions, granulomas were composed of 14.19 ± 2.43% of CD4+ T cells, 12.51 ± 2% of CD8+ T cells, 2.84 ± 0.57% of B cells, and 11.18 ± 1.81% of CD68+ macrophages." (PMID 31475008, 2019). "In the compiled data comparing the non-vaccinated group to the BCG-vaccinated group, in INH treated granulomas, there was a significant increase in CD4 expression in the BCG-vaccinated groups in most categories, except for MIC and 1/10 INH + L-GSH." (PMID 31569759, 2019). "Our further study will use the silk fibroin to replace Alum adjuvant to extend the CD4+ Trm cell distribution, increase their magnitudes, and prevent the form of granuloma." (PMID 31156652, 2019). "In comparison to the non-vaccinated group, PZA treatment resulted in a significant increase in CD4 expression in the granulomas from BCG-vaccinated groups." (PMID 31569759, 2019). "The addition of L-GSH to granulomas from BCG-vaccinated subjects lead to increased CD4 T cell viability, increased TNF-α and IFN-γ production, decreased PD-1 expression, and diminished T cell exhaustion." (PMID 31569759, 2019). "IL-10 has been shown to mediate this down-regulation via an activation-induced cell death process resulting in apoptosis of CD4+ and CD8+ T cells which is also linked to the onset of egg-laying by the helminth parasite and formation of granulomas." (PMID 30048550, 2018). "Nevertheless, CFU- LNs with granulomas had significantly higher proportions of CD11b+ cells producing IL-10 when compared with CFU+ LNs with granulomas, while CD4+ T cells producing TNF were significantly higher in CFU+ LNs." (PMID 30383808, 2018). "Another subset of T-cells, Th17 effector CD4 (+), which mediate the crosstalk between immune cells and tissues, has been shown to participate in the progression of granulomas and in the fibrotic phase of the disease." (PMID 29510755, 2018). "Primary granulomas contained a preponderance of CD4+ T cells while the early infiltrate lesions contained more CD8+ T cells." (PMID 30283448, 2018). "Granulomas were mainly comprised of CD4+ cells and CD68+ cells, indicating that the granulomas were formed by accumulation of CD4+ T lymphocytes and macrophages." (PMID 29123243, 2017). "Our data additionally highlight the potential utility of low CD45RA+ (<20% CD4+ cells) in subcategorizing CVID patients at risk for lymphoproliferative complications including LAD, granulomas, autoimmune hepatitis, and GLILD." (PMID 29375540, 2017). "Granuloma formation is the result of a host adaptive immune response mediated by CD4+ T cells specific for Schistosome egg Ags (SEA), which damaged hepatocytes and destroyed the normal histological structure of the liver." (PMID 28539607, 2017). "Granuloma was among the most common pathological result of pulmonary lesions in cryptococcosis patients; this was mainly induced by CD4+ T-cell immunity." (PMID 28035481, 2017). "In contrast, M. mass-induced in vitro granulomas exhibited a decrease in not only CD4+, but also CD8+ T cells." (PMID 27489303, 2016). "CD3+, CD8+, and CD4+ T cells were evenly distributed within the lymphocyte layer of the granulomas in each group." (PMID 27462092, 2016). "Microscopic features between the two groups are similar but an inverted CD4 : CD8 lymphocyte ratio is seen within the granulomas of patients coinfected with HIV." (PMID 27366339, 2016). "Peripheral CD4+ T-cell depletion correlated with granulomas that contained fewer CD4+ and CD8+ T cells, less interferon γ, more neutrophils, more interleukin 10 (IL-10), and increased M. tuberculosis numbers." (PMID 27462092, 2016). "Coinfected persons with <50 peripheral CD4+ T cells/μL of blood showed significantly lower granuloma CD4+ T-cell counts than in M. tuberculosis–monoinfected persons or those with >200 peripheral CD4+ T cells/μL of blood." (PMID 27462092, 2016). "These granulomas were also more likely to contain fewer CD4+ T cells and lower CD4+/CD8+ T-cell count ratios." (PMID 27462092, 2016).
Granuloma (continued). "The significant neutrophil debris staining within caseum, especially within peripheral CD4+ T-cell–depleted persons, suggests that neutrophils are actively migrating into granulomas." (PMID 27462092, 2016). "The histopathological pattern is mostly affected by the immune state, and HIV-infected persons with severely depleted CD4 lymphocytes present with less granuloma on biopsy." (PMID 27899066, 2016). "Th2 immunity involves the rapid activation and engagement of cells of both the innate (eosinophils and basophils) and adaptive (CD4+ T cells committed to the Th2 pathway) immune systems, and constitutes a crucial factor in the generation of granuloma." (PMID 26191954, 2015). "While the worms themselves evade immune destruction, eggs are highly antigenic and not only require a strong CD4 T cell response for efficient release, but also incite the formation of CD4 T cell-containing granulomas in intestinal tissue." (PMID 26335139, 2015). "Granuloma formation in the liver in response to Leishmania requires the recruitment of CD4+ T cells and the release of IL-12, IFNγ and TNF, among other cytokines." (PMID 26684322, 2015). "Differential labeling of CX3CR1-GFP+ cells in the blood and the tissue showed CD4+ T cell dependent accumulation of PD-L2+ CX3CR1-GFP+ AAM in the tissues as granulomas form." (PMID 24967715, 2014). "The granulomas are characterized by a central area of activated macrophages surrounded by activated CD4+ T cells." (PMID 25230725, 2014). "Lymphocytes scattered within granulomas tend to be CD4+ T helper cells, while those around the periphery are CD8+ T cells and to a lesser extent B cells." (PMID 25250336, 2014). "Granuloma formation is the result of a host adaptive immune response mediated by CD4+ T cells specific for schistosome egg antigens (SEAs) that damages hepatocytes and destroys the normal histological structure of the liver." (PMID 24466157, 2014). "Granuloma formation and the resulting pathology are dependent on and are mediated by CD4+ T cells responding to egg antigens." (PMID 24466157, 2014). "Granuloma formation is mainly mediated by CD4+ T cells specific for the parasite antigens, and these cells also participate in the modulatory process of granuloma development." (PMID 24348679, 2013). "The role of DCs in antigen presentation to CD4+ T cells in granulomas during EVL remains to be addressed." (PMID 23423646, 2013). "By week 10, iNOS−/− mice showed increased fungal burdens circumscribed, however, by compact granulomas containing elevated numbers of activated CD4+ T cells." (PMID 23936574, 2013). "As antigen-specific CD4 T cells are critical to human granuloma formation, it would be of value to investigate if enhanced priming of CD4 T cells would enhance T cell migration into inflammatory sites leading to formation of more rigorous, structured lesions." (PMID 24313934, 2013). "The granulomas around the trapped eggs are composed of collagen fibers and inflammatory cells of Th2 origins, including eosinophils, macrophages and CD4+ T-cells." (PMID 23849678, 2013). "Accumulating evidence has suggested that CD4+ T cells, particularly CD4+ T helper 1 (Th1) lymphocytes, play a major role in immune-mediated development and accumulation of granulomas." (PMID 24177566, 2013). "IFN-γ-producing CD4 T lymphocytes contribute to the generation of granulomas, besides being important costimulators to the adequate activation of CD8 T lymphocytes." (PMID 23251798, 2012). "The central part of a granuloma is composed of macrophages, modified macrophages, epithelioid cells and giant cells, with scattered, predominately CD4+ T, lymphocytes between them." (PMID 22958359, 2012). "CD4+ T cells interact with antigen presenting cells which initiate the formation and maintenance of granulomas, resulting in differentiation of selective Th1 cells secreting IFN-γ and IL-2." (PMID 23320239, 2012).
Granuloma (continued). "CD4+Foxp3+ T cells were increased in the granulomas and perivascular areas of the liver in the chronic phase and the impairment of granuloma maturation was observed." (PMID 22928057, 2012). "In natural conditions, the CD4+ T cells of the granuloma have a diverse TCR repertoire, but reconstitution with a monoclonal population of CD4+ T cells is sufficient to restore granuloma formation." (PMID 22811737, 2012). "Despite very low antigenic availability following BCG vaccination, CD4+ T cell priming still was observed as a result of dendritic cell migration from the site of chronic granuloma formation to systemic sites and lymphoid organs." (PMID 22844428, 2012). "CD4+ T lymphocytes predominate in the inner layer of the granuloma periphery and CD8+ T lymphocytes in the outer one." (PMID 22958359, 2012). "Regarding lymphocyte distribution in and around granulomas, CD4/CD8 T cell ratios were 2.3, 1.1, and 2.0, respectively, at abscesses, granulomas, and outer layers of granulomas." (PMID 22588497, 2012). "The granuloma is a typical structure of this disease, where we can find CD4 and CD8 T lymphocytes, B lymphocytes, macrophages, neutrophils, fibroblasts, and giant multinucleated cells." (PMID 23251798, 2012). "Previous studies in the experimental autoimmune encephalomyelitis (EAE) model have shown that infection with BCG 6 weeks before the induction of EAE diverts activated myelin-reactive CD4+ T cells from the CNS to granulomas in the spleen and liver." (PMID 21304945, 2011). "Mycobacterial antigen presentation via MHC class II molecules is critical for the recruitment of additional CD4+ T cells and the formation and maintenance of granulomas." (PMID 22182502, 2011). "T cell activation is mandatory for the development of granulomatous reactions and CD4+ T cells of the Th1-type are essential for the formation and the maintenance of granulomas." (PMID 21251246, 2011). "Here, we showthat multiple (4x) exposures, prior to the onset of egg laying by adult worms,modulate the skin immune response and induce CD4+ cellhypo-responsiveness in the draining lymph node, and even modulate the formation ofhepatic egg-induced granulomas." (PMID 21445234, 2011). "CD4+ cells were present at significantly less frequency compared to numbers seen in granulomas (P < .05)." (PMID 21197439, 2011). "Histology shows granulomas consisting of a central zone with macrophages, epithelioid cells, and multinucleated giant cells in addition to activated CD4 lymphocytes, and a peripheral zone with macrophages, fibroblasts, and CD4 and CD8 lymphocytes." (PMID 21345227, 2011). "In parallel with the development of the granulomas, the proportion of Th17 cells in splenic CD4+ T cells increased very slowly during the first five weeks post-infection compared to that before infection (week 0) and increased rapidly thereafter." (PMID 22102924, 2011). "CD11c+ cells purified from three-week granulomas were more efficient at inducing IFNγ and IL-2 production from OT-II CD4+ T-cells than CD11c+ cells from ten-week granulomas." (PMID 20625513, 2010). "Since many current therapeutic efforts are aimed at generating an increase in Mtb-specific IFNγ-producing Th1 cells, we next tested the ability of DCs to re-boost newly recruited CD4+ T cells in acute and chronic granulomas." (PMID 20625513, 2010). "CD4+ T cells from ten-week granulomas showed a dramatic decrease in both IFNγ production and LFA-1 expression compared to three-week granulomas." (PMID 20625513, 2010). "After this initial phase of granuloma development, a CD4+ cell response begins to exert a dominant effect on the pathology and the requirement for B cells is alleviated." (PMID 18320044, 2008). "The antimycobacterial immune response was characterized by well-formed granulomas with a low organism load, increased CD4/CD8 ratio in the granulomas, and marked TNF-α production." (PMID 18477401, 2008).
Granuloma (continued). "Furthermore, the localisation of CD4 lymphocytes, predominantly in granulomas, and CD8 lymphocytes, sporadically at the periphery of granulomas, is a pathological feature of CS." (PMID 40226537, 2025). "Additionally, predominant infiltration of CD4+ lymphocytes, which is pronounced in the vicinity of the granulomas, has been reported." (PMID 40928208, 2025). "Importantly, CD4 depletion in CoMtb mice completely reversed alveolitis formation and resulted in necrotic granulomas with large central aggregates of neutrophils expressing CXCL2, similar to primary granulomas observed without CoMtb." (PMID 40736456, 2025). "Furthermore, we identified tissue-resident memory T cells (TRM) either expressing CD4 or CD8 within necrotizing granulomas." (PMID 40843005, 2025). "Granuloma formation remains preserved even in patients with low CD4+ T-cell counts." (PMID 40559189, 2025). "The model interestingly provides new evidence about the role of that pathogen in granuloma occurrence by showing granuloma-like structure formation after P. acnes infection of PBMCs, also leading to a CD4+ or CD8+ T-cell immune response according to the bacterial strain." (PMID 39996765, 2025). "A higher CD4+ T cell count was more likely to result in fully formed granulomas, while a lower count may lead to poorly formed or unformed granulomas." (PMID 39205309, 2024). "For example, a 2016 clinical study in Africa suggested that reduced levels of peripheral blood CD4+ T lymphocytes could change the phenotype of immune cells within granulomas, thereby altering granuloma structure and morphology." (PMID 39205309, 2024). "It is a curious observation that T cells are dispensable during primary infection because in Mycobacterium tuberculosis-induced granulomas, CD4+ T helper type 1 (Th1) cells are required to stimulate the antibacterial activity of macrophages (Pagán & Ramakrishnan, 2018)." (PMID 38352492, 2024). "It is a curious observation that T cells are dispensable during primary infection because in Mycobacterium tuberculosis-induced granulomas, CD4+ T helper type 1 (Th1) cells are required to stimulate the antibacterial activity of macrophages (Pagán and Ramakrishnan, 2018)." (PMID 39541153, 2024). "Due to the functional impairment of macrophages and dendritic cells and the depletion of CD4+ T lymphocytes caused by HIV infection, the trajectory of granulomas may be affected by HIV infection." (PMID 39205309, 2024). "CD4+IFNγ+ T cells are critical in the formation of granulomas with early containment of Mtb." (PMID 39717773, 2024). "They reported more poorly formed granulomas in those with lower peripheral CD4+ counts." (PMID 39066368, 2024). "Additionally, a positive correlation was found between peripheral blood CD4+ T cell counts and the proportion of CD4+ T cells in granuloma tissues." (PMID 39205309, 2024). "Furthermore, in addition to their direct functions in the response to infection, CD8+ T cells also play an important role in organizing optimal CD4+ T-cell function in granulomas." (PMID 39065554, 2024). "To determine whether the three types of lymphocytes could affect the integrity of granulomas, we conducted a semi-quantitative analysis of the completeness of granulomas and the presence of CD4+, CD3+, and CD8+ T cells in biopsy tissues." (PMID 39205309, 2024). "This has shown that the predominant T cell subtype in all stage of granulomas is CD4+ T cells." (PMID 37901102, 2023). "CD8+ T cells have a peripheral localization in granulomas, while CD4+ T cells occupy their center." (PMID 37761328, 2023). "Identifying Mtb-specific CD4 T cells in thoracic lymph nodes, lungs, and granulomas." (PMID 37039646, 2023). "Additionally, a significantly higher (P < 0.0001) percentage of Th17 responses (CCR6+CD4+ T cells) was observed in the granulomas of the cART/2-week group." (PMID 34855621, 2022).